CRP (C-reactive protein)
Diseases named in the same sentence as CRP in open-access papers (continued):
Sharing a sentence is not in itself a finding about the gene and the disease.
ulcerative colitis (continued). "AP treatment was safe and was associated with short-term clinical improvement and reduction of C-reactive protein in ulcerative colitis." (PMID 23231745, 2012). "An uncontrolled trial in adults with ulcerative colitis showed that administration of oral AP for seven days resulted in decreased CRP levels and improved clinical response scores." (PMID 22906145, 2012). "When the IBD patients were evaluated as ulcerative colitis and Chron’s disease seperately, CD group showed higher levels of CRP and ESR." (PMID 27942288, 2010). "Of note, the analysis did identify a statistically significant association between knee involvement and elevated C-reactive protein (CRP, odds ratio [OR] 4.3; 95% confidence interval [CI] 1.18–21.0; p = 0.04) and endoscopically active ulcerative colitis (UC) (OR, 5.9; 95% CI, 1.16– 37.0; p = 0.04)." (PMID 40658153, 2025). "In ulcerative colitis patients, only a modest increase in CRP is observed, and it is estimated that ~15% of patients in the general population may not show a CRP response due to genetic heterogeneity in CRP responses." (PMID 41374379, 2025). "CRP levels could also be lowered due to a decreased expression of IL-6, and it has been reported that probiotic consumption lowers IL-6 expression in ulcerative colitis patients." (PMID 40859402, 2025). "Fecal calprotectin (FC) and C-reactive protein (CRP) are noninvasive biomarkers used in ulcerative colitis (UC) clinical trials; however, thresholds defined as “normal” in trials may be higher than “normal” thresholds typically used in clinical practice." (PMID 40589947, 2025). "Patients with ulcerative colitis only had higher levels of erythrocyte sedimentation rate (p = 0.000), CRP (p = 0.000), triglyceride (p = 0.000), Ag PLT ADP (p = 0.000), leukocyte (p = 0.001), fecal calprotectin (p = 0.000), IL-6 (p = 0.000), and TNF-α values (p = 0.000) than healthy controls." (PMID 36984554, 2023). "The change in CRP was the same in patients with ulcerative colitis." (PMID 36618924, 2022). "Also, synbiotics were more effective compared with prebiotics and probiotics alone in reducing C-reactive protein and improving social and systemic function in ulcerative colitis." (PMID 35942243, 2022). "Some clinical and pre-clinical studies also demonstrated that ulcerative colitis could lead to a significant increase in serum inflammatory factors, such as IL-17A, IL-6 and CRP." (PMID 35267960, 2022). "Our findings indicate that the serum gelsolin level correlates with clinical and endoscopic activities in ulcerative colitis, has a higher sensitivity and specificity than C-reactive protein, and can detect mucosal healing, suggesting that gelsolin can be used as a biomarker for ulcerative colitis." (PMID 35453622, 2022). "This study aimed to evaluate whether serum amyloid A is a better serum biomarker than C-reactive protein in predicting mucosal healing in ulcerative colitis patients in clinical remission." (PMID 32245401, 2020). "Ulcerative colitis patients whose C-reactive protein and serum amyloid A were measured within 1 month before and after colonoscopy were included in this retrospective study, and the relationship between the C-reactive protein and serum amyloid A values and the mucosal condition was analyzed." (PMID 32245401, 2020). "In patients with ulcerative colitis, urinary GSA correlated with ELISA fMPOp (r = 0.45, P < .0001), ELISA fMPOa (r = 0.45, P < .0001), fCal (r = 0.61, P < .0001) and CRP (r = 0.29, P = .01)." (PMID 40411448, 2025). "The Ulcerative Colitis Endoscopic Index of Severity (UCEIS) and C-reactive protein (CRP) level at Day 3 are independent predictors of IVCS resistance." (PMID 36196253, 2022). "A total of 4 literatures measured the improvement of ulcerative colitis by the levels of inflammatory factors (IL-6, TNF-α, and CRP)." (PMID 35912148, 2022).
ulcerative colitis (continued). "Our results suggest that, in contrast to C-reactive protein and mean platelet volume, M30 levels do not have a significant role as an activation marker in ulcerative colitis patients." (PMID 39292076, 2024). "The existing body of evidence does not offer adequate support for the direct implication of CRP in modulating the advancement of ulcerative colitis." (PMID 39380742, 2024). "Levels of CRP, FC, LRG and stool lactoferrin (SL) are useful noninvasive markers of inflammation, although FC appears a stronger predictor of relapse in patients with ulcerative colitis than in patients with CD." (PMID 36773075, 2023). "A prospective study of 267 IBD patients (203 ulcerative colitis cases and 64 CD cases) comparing the levels of LRG with CRP and FCal against clinical and endoscopic disease activity has shown similar detectability of endoscopic inflammation between FCal and LRG in CD patients." (PMID 38069288, 2023). "Our study shows higher levels of SE, CRP, Ag PLT ASPI, Ag PLT TRAP, Ag PLT ADP, Le, PLT, FCP, TNF-α, and IL-6 in patients with ulcerative colitis, when compared to the healthy controls, as well as lower levels of vitamins B12, B6, serum Fe, and transferrin saturation." (PMID 36984554, 2023). "In non-specific chronic colitis, CRP examination is less effective in establishing a diagnosis without the help of other examinations, although it shows significant results in ulcerative colitis." (PMID 36873123, 2023). "Dietary curcumin supplementation could significantly improve the clinical outcomes, life quality, high-sensitivity C-reactive proteins (hs-CRP) and the erythrocyte-sedimentation rate (ESR) in patients with ulcerative colitis." (PMID 36982944, 2023). "We aimed to analyze the dependence of RUNX3 promoter 2 (P2) methylation level on: age, sex, body mass index (BMI), C-reactive protein (CRP), serum albumin, disease duration, Pediatric Ulcerative Colitis Activity Index (PUCAI), the Paris classification, and exposure to medications." (PMID 36140736, 2022). "In the same way, a cross-over study among 17 patients with ulcerative colitis (UC) has revealed that a 4-week low-fat diet may be able to improve QOL, as well as decreasing CRP." (PMID 36777780, 2022). "An uncontrolled phase 2 trial of intraduodenal alkaline phosphatase in patients with ulcerative colitis demonstrated reductions in C-reactive protein, fecal calprotectin, and clinical activity indices with no particular safety concerns identified." (PMID 29515999, 2018). "Finally, some patients with ulcerative colitis lacked recent systemic inflammatory markers, such as CRP, ESR, and fecal calprotectin, at the time of enrollment, which resulted in this study not analyzing laboratory indicators of inflammation." (PMID 41601538, 2026). "In ulcerative colitis, CRP does not consistently change following probiotic therapy." (PMID 41356879, 2025). "Additionally, eliminating intestinal bacteria flora interference through antibiotic treatment revealed that mice lacking CRP did not demonstrate any notable variations in the ulcerative colitis model." (PMID 39380742, 2024). "This meta-analysis also showed that probiotics can improve the endoscopic score of ulcerative colitis patients, improve the overall response rate (reduce inefficiency), reduce disease activity, and reduce CRP and ESR levels, and there are no obvious adverse events." (PMID 38475833, 2024). "Additionally, previous studies have reported that compared to CRP levels, serum LRG levels have a stronger correlation with disease activity in ulcerative colitis, and that serum LRG is clinically used for disease activity monitoring in inflamatory bowel diseases (IBD)." (PMID 36812242, 2023). "Furthermore, the mean level of CRP in subjects with chronic non-specific colitis was 13.54±8.09 mg/L and 15±4.24 mg/L in ulcerative colitis." (PMID 36873123, 2023).
ulcerative colitis (continued). "FCP and CRP tended to correlate more strongly with the sum of Mayo Endoscopic Subscore (S-MES) and Ulcerative Colitis Colonoscopic Index of Severity (UCCIS) than with maximum Mayo Endoscopic Subscore (M-MES) and Ulcerative Colitis Endoscopic Index of Severity (UCEIS)." (PMID 34947906, 2021). "Another study found that there was no relation between serum CRP and endoscopic activity of ulcerative colitis (UC), and ESR was the more accurate to assess the endoscopic activity than CRP with low sensitivity and specificity." (PMID 36157220, 2022). "However, CRP trajectories were not analyzed, which is another biomarker emphasized in the STRIDE II cohort, and patients with ulcerative colitis (UC) were excluded." (PMID 40314771, 2025). "Additionally, C-reactive protein (CRP) levels demonstrated inconsistent patterns to treatment responses; meanwhile, elevated CRP levels in CD patients aligned with improved responses to anti-TNF therapies and yet exhibited a negative correlation in ulcerative colitis (UC) patients." (PMID 40149684, 2025). "Although one waitlist control RCT found decreases in CRP among non-flared ulcerative colitis patients following an 8-week Mindfulness-Based Stress Reduction (MBSR) course, other RCTs–with and without active treatment control groups–have shown non-significant reductions in CRP." (PMID 31295270, 2019).
vasculitis (161 papers, 2009 to 2025). "Physician G-DAS correlated with Birmingham Vasculitis Activity Score (V3.0; R 0.42, p 0.046) and were significantly linked to serum CRP elevations (β = 0.04, CI 0.0-0.08, p 0.028)." (PMID 38285076, 2024). "GWAS studies identified the FCGR2A-131H allelic variant with lower affinity for CRP as a susceptibility marker for Kawasaki disease in male patients, a pediatric vasculitis associated with coronary artery aneurysms." (PMID 35203703, 2022). "In clinical characteristics, we found that IKBKE mRNA expression levels were associated with vasculitis (P = 0.015) and increased C-reactive protein (CRP) (P = 0.021) in SLE patients." (PMID 32146614, 2020). "In multivariable linear regression, age < = 69 years, previous relapse of vasculitis, elevated CRP and lower knee extension force were associated with lower age-adjusted physical quality of life, with a total adjusted R2 of 0.55 for the regression model." (PMID 30716132, 2019). "Moreover, CRP also stimulates platelet aggregation, epithelial cell activation, and vascular permeability, which can cause vasculitis." (PMID 41169895, 2025). "Furthermore, investigating coagulation factors, markers of inflammation (such as erythrocyte sedimentation rate (ESR) and CRP), and screening for underlying vasculitis is achieved through tests for antineutrophilic antibody and antineutrophil cytoplasmic antibody." (PMID 40535409, 2025). "FDG–PET may visualize some rare drug-induced findings, For example, pegfilgrastim, a long-acting pegylated G-CSF, can induce vasculitis that causes antibiotic-resistant fever and high C-reactive protein levels in patients treated with pegfilgrastim for leukocytopenia due to chemotherapy." (PMID 36575286, 2023). "Most studies noted that patients with IgG4-related coronary arteritis were more likely to exhibit elevated serum CRP compared to those with non-vasculitis IgG4-RD or other autoimmune arteritis." (PMID 41425560, 2025). "In AAV patients, SOD levels negatively correlate with markers such as the erythrocyte sedimentation rate (ESR), C-reactive protein (CRP), and the Birmingham Vasculitis Activity Score (BVAS), suggesting that SOD decreases as inflammation intensifies." (PMID 40867576, 2025). "Elevated levels of serum CRP and CRP expression agree well with the clinical and histopathological findings of vasculitis, intima proliferation and thrombosis in SINS and support the assumption of SINS as a vascular disease." (PMID 39825377, 2025). "In our case report, the patient also complained of back pain and, given the fever and the gradual decline in CRP, vasculitis was suspected." (PMID 41374458, 2025). "Taking into account the observed associations between age and CRP level changes with SCP-VD, therefore, we have considered that the reduction of SCP-VD is associated with vasculitis." (PMID 40589745, 2025). "The assessments included body mass index, fat and lean mass percentages, waist-to-hip ratio, C-reactive protein, erythrocyte sedimentation rate, and disease activity using the Birmingham Vasculitis Activity Score." (PMID 39712710, 2024). "Vasculitis with variable organ involvement and systemic inflammation was noted in majority of patients, and CRP appears to be a more sensitive index for inflammation compared to ESR." (PMID 36807221, 2023). "Compared with the ANCA-negative group, the MPO-ANCA–positive group had higher CRP and percentage of vasculitis suggested by sural nerve biopsy but lower eosinophil infiltration in affected tissues." (PMID 35833130, 2022). "Meanwhile, persistant fever and clearly increased CRP have been known to reflect the extent of systemic inflammation and vasculitis in KD patients." (PMID 35989868, 2022). "We only included patients with established GPA, suggesting that a degree of cardiac inflammation is present throughout the GPA disease continuum, and, in our cohort, an association between native T1 and vasculitis-related damage (VDI) and inflammation (CRP)." (PMID 33057879, 2021).
vasculitis (continued). "The cut-off for distinguishing the active phase in long-term remission for CRP was 1.4 mg/dl, whereas for distinguishing active vasculitis from other diseases was 0.8 mg/dl." (PMID 33664330, 2021). "Model 1 included the ANCA phenotype, items of the Birmingham Vasculitis Activity Score, and interstitial lung disease; model 2 included serum creatinine (s-Cr) and C-reactive protein (CRP) levels with model 1 components." (PMID 33664381, 2021). "The markers of vasculitis, such as CRP, interleukin 6, D-dimer, and natriuretic peptide, are elevated in serum." (PMID 34682178, 2021). "LAMP-2-ANCA titers were also not correlated with elevated systemic disease activity as indicated by a validated pediatric vasculitis clinical scoring algorithm, pVAS, and general inflammatory markers, CRP and ESR." (PMID 33613565, 2020). "We found that 18F-FDG-PET/CT positivity was significantly associated with a lower dose and shorter duration of GC medication and higher CRP level in vasculitis patients." (PMID 31531005, 2019). "A higher proportion had a severe form (p = 0.001) and granulomatosis with polyangiitis (GPA) (p = 0.001), as well as a higher Birmingham Vasculitis Activity Score (p = 0.018) and C-reactive protein (p = 0.018) levels at baseline." (PMID 31291263, 2019). "Among all 82 patients with suspicion of vasculitis, C-reactive protein (CRP) was elevated in 75 patients (91.5%), with a mean CRP value of 129.0 mg/L (SD = 89.5 mg/L)." (PMID 31531005, 2019). "The second group had more frequent fever (68% versus 22%, p=0.001), vasculitis-like skin lesions (27% versus 0%, p=0.005), and higher CRP level at disease onset (30.461±21.51 versus 16.25±20.9, p=0.039)." (PMID 30498759, 2018). "Active vasculitis directly before the start of tocilizumab was properly documented in all patients by CRP (n=6), ESR (n=7), CDU (n=5), MRI (n=4), and PETCT (n=3)." (PMID 30258504, 2018). "Inflammatory markers such as ESR, CRP were significantly increased, suggesting many of them were at the active stage of vasculitis when pneumothorax occurred." (PMID 29334967, 2018). "Patients with active vasculitis had a mean CRP of 5.02 +- 5.87 mg/dl and a mean ESR of 58.2 +-45.9 mm/h." (PMID 30258504, 2018). "In the presence of active BD, such as in patients with IBD or other forms or vasculitis, levels of serum markers of inflammation, C-reactive protein and erythrocyte sedimentation rate, are elevated." (PMID 28427473, 2017). "The urinary levels of HMGB1 correlated with erythrocyte sedimentation rate (ESR) (r = 0.354, p = 0.012), C-reactive protein (CRP) (r = 0.289, p = 0.042), and Birmingham Vasculitis Activity Score (BVAS) (r = 0.350, p = 0.013)." (PMID 25884225, 2015). "Further analysis found that urinary levels of HMGB1 correlated with erythrocyte sedimentation rate (r=0.354, p=0.012), C-reactive protein (r=0.289, p=0.042), and Birmingham Vasculitis Activity Score (r=0.350, p=0.013)." (PMID 25884225, 2015). "Testosterone, age, vasculitis damage index (VDI) and C-reactive protein (CRP) were associated with the MFI-20 subscale of general fatigue." (PMID 24028544, 2013). "The two patients with normal CRP levels demonstrated classic histopathologic features including geographic necrosis, palisading granulomas, vasculitis, or microabscesses, which supported the clinicopathologic diagnosis of GPA despite the normal CRP level." (PMID 22577389, 2012). "sRAGE levels were negatively associated with serum levels of C-reactive protein (CRP) and high-density lipoprotein (HDL), history of vasculitis, and the presence of the RAGE 82Ser polymorphism." (PMID 19284577, 2009). "Similarly, CRP and MPO-ANCA were incorporated as explanatory variables based on their known associations with vasculitis severity and renal prognosis." (PMID 40136450, 2025). "The laboratory data included elevated white blood cell counts and CRP levels, which may have led some participants to suspect a diagnosis of vasculitis or leukemia." (PMID 41220543, 2025).